CRP (C-reactive protein)
Diseases named in the same sentence as CRP in open-access papers (continued):
Sharing a sentence is not in itself a finding about the gene and the disease.
cardiovascular disease (continued). "For example, ginger has a significant effect on reducing circulating C-reactive protein (CRP) and tumor necrosis factor-alpha (TNF-α) levels, which are systemic inflammatory markers associated with an increased risk of cardiovascular disease." (PMID 34055012, 2021). "Inflammatory markers such as C-reactive protein and procalcitonin have been shown to be independent markers of cardiovascular diseases." (PMID 34725609, 2021). "Studies show that IL-6 is a biomarker with better sensitivity and characteristics than CRP for the diagnosis of cardiovascular disease." (PMID 33436103, 2021). "C-reactive protein (CRP) is an acute-phase protein that is stimulated by pro-inflammatory cytokines; and it is a biomarker of systemic inflammations and cardiovascular disease." (PMID 34062965, 2021). "We propose to measure the area-under-the-curve for C-reactive protein (CRP) as the preferred pro-inflammatory marker in cardiovascular disease." (PMID 33902621, 2021). "We used a nested case–control study to assess the effect of hs-CRP in the short-term prediction of cardiovascular disease outcomes in the Iranian population." (PMID 33407576, 2021). "AGE levels are an independent predictor of overall and cardiovascular mortality as pre-existing cardiovascular disease, C-reactive protein, and serum albumin during a three-year follow-up in 109 HDF patients." (PMID 33921921, 2021). "In this study we found a differential association pattern between the level of the various IGFBPs under study with markers of oxidative stress (Ox-LDL) and cardiovascular diseases (Hs-CRP)." (PMID 34394011, 2021). "The expression of CRP increases during inflammatory conditions, for instance, rheumatoid arthritis, infection, and special cardiovascular diseases." (PMID 33564690, 2021). "CRP possesses proatherogenic properties similar to those of the inflammation process and, thereby, can influence the pathogenesis of cardiovascular diseases." (PMID 33498799, 2021). "GDF-15 was an independent risk factor for cardiovascular disease in AGHD patients below 60 years of age after adjusting for other cardiovascular risk factors such as BMI, HOMA-IR, LDL-C, and hs-CRP by binary logistic regression (P < 0.05)." (PMID 34394348, 2021). "The model including age > 65 years, male sex, cardiovascular disease, dyspnoea and at least three abnormal blood parameters among CRP (> 80 U/L), ALT (> 40 U/L), NLR (> 4.5), LDH (> 250 U/L), and CK (> 80 U/L) shows fair discrimination ability (AUC 0.73)." (PMID 34454452, 2021). "By using high-sensitive technique and a different reference interval, CRP can reflect low-grade inflammation with clinical implications, e.g. cardiovascular diseases." (PMID 34408755, 2021). "Traditional markers such as C-reactive protein (CRP) and homocysteine, along with more novel ones, specifically microRNAs (miRNAs), can accurately signal the risk of cardiovascular disease (CVD) in PCOS women." (PMID 33679617, 2021). "After recognizing the value of CRP in predicting cardiovascular diseases, its proper function began to draw attention from many researchers." (PMID 33498799, 2021). "Increased levels of CRP in dogs with various cardiovascular diseases and CHF have also been found in other studies." (PMID 33902566, 2021). "Furthermore, damage to the walls of the vessels can be caused by infiltration into the cell wall and inflammatory elements, for this reason, CRP levels can be used to establish the level of risk of cardiovascular disease and its increase could also highlight the presence of genetic pathologies." (PMID 32781561, 2020). "While baseline CRP levels in the healthy state are established as predictor of the incidence of cardiovascular disease, serum CRP concentration during and after AMI correlates with clinical outcome." (PMID 32932587, 2020).
cardiovascular disease (continued). "Regarding inflammatory status as indicated by hs-CRP baseline serum levels, our study population was in-between a general population and a population with cardiovascular disease." (PMID 33264342, 2020). "Acute phase response is an established risk factor for cardiovascular disease and blood levels of SAA and C-reactive protein (CRP) are risk factors for cardiovascular disease in prospective epidemiological studies." (PMID 32450889, 2020). "Hs-CRP levels have emerged as a useful biomarker for atherosclerotic processes and future cardiovascular disease (CVD) risk, acting as a more sensitive alternative to the traditional CRP marker." (PMID 33182500, 2020). "C-reactive protein and other markers of inflammation in the prediction of cardiovascular disease in women." (PMID 32308931, 2020). "Over recent years, evidence has emerged linking CRP to the development and progression of chronic, auto-inflammatory diseases such as cardiovascular disease." (PMID 32117266, 2020). "Compared with DNAm PhenoAge, DNAm GrimAge includes more clinical biomarkers, such as cardiovascular disease related plasma proteins (e.g. C-reactive protein, and growth differentiation factor-15)." (PMID 32561690, 2020). "CRP is an important biomarker for various cardiovascular diseases and its determination requires sensitive and accurate methods with high selectivity for application in complex clinical samples." (PMID 32660011, 2020). "Various markers of inflammation especially CRP have been shown to be associated with a higher predisposition to T2DM and consequent cardiovascular disease." (PMID 32984066, 2020). "Sustained increases in CRP, an acute phase protein normally produced by the liver during acute infection in response to IL-6, IL-1β or TNF-α, indicate increased risk for cardiovascular disease." (PMID 32245117, 2020). "CRP levels have been used in cardiovascular disease to identify and monitor patients with ongoing inflammation, for example in atherosclerotic plaque formation." (PMID 31858023, 2019). "CRP is more commonly studied, especially in relation to cardiovascular disease in the developed world, but also in pregnancy." (PMID 31469064, 2019). "Recently, in addition to the pentameric isoform, CRP has been detected as a trimer and a tetramer in blood of patients with cardiovascular disease, as well as in the blood and other tissues of human CRP transgenic rats." (PMID 31151201, 2019). "In previous studies, inflammatory and oxidative factors, such as C-reactive protein (CRP) and red blood cell distribution, have been thought to be related to cardiovascular disease." (PMID 30850753, 2019). "CRP has been described as a biomarker of the inflammatory response with significant prognostic value in a vast number of tumors and rheumatic and cardiovascular diseases." (PMID 31281384, 2019). "Clinical studies suggest that suPAR has an additive value to high-sensitivity C-reactive protein (hsCRP) or interleukin-6 (IL-6) in characterizing systemic inflammation in cardiovascular diseases." (PMID 30820636, 2019). "The CRP is an acute phase plasma protein used to diagnose chronic inflammatory diseases, and it is related to the development of cardiovascular disease (CVD) and atherosclerosis." (PMID 31143476, 2019). "Among the inflammatory factors, high-sensitivity C-reactive protein (hs-CRP) is one of the strongest predictors of cardiovascular disease." (PMID 31814938, 2019). "The low grade of the inflammation developed in the fructose group and expressed by a high level of plasma CRP, a powerful indicator of inflammation and a predictor for cardiovascular diseases, can be multifactorial." (PMID 31835800, 2019). "In this sense, %BF below the health risk value helps to control low-grade inflammation in the arterial wall, that is, it contributes to avoid the inflammatory action of CRP and IL-6, whose non action consequently helps avoiding cardiovascular diseases." (PMID 30624536, 2019).
cardiovascular disease (continued). "Because the measurement of low concentrations of CRP is critical for early diagnosis of inflammation and cardiovascular disease, many researchers have attempted to develop a highly sensitive CRP-detectable LFIA." (PMID 31673811, 2019). "In patients with cardiovascular diseases, β-carotene was significantly correlated with IL-6 and CRP." (PMID 30991720, 2019). "As such, elevated inflammation markers such as C-reactive protein have been shown to be predictive of cardiovascular disease and cardiovascular events suggestive of ongoing mild systemic inflammation in these patients." (PMID 31906053, 2019). "Associations with APS characteristics, classic cardiovascular disease (CVD) risk factors, high-sensitivity CRP (hs-CRP) and high-sensitivity Troponin (hs-TnT) levels were tested." (PMID 31340567, 2019). "The CRP—an acute-phase reactant secreted by the liver—has emerged as an independent predictor of cardiovascular disease, type 2 diabetes, and chronic kidney disease." (PMID 30813467, 2019). "Low-grade inflammation produced by C-reactive protein (CRP) and interleukin-6 (IL-6) cytokine is a predictor of the risk for cardiovascular diseases." (PMID 30624536, 2019). "CRP is used as a clinical marker of inflammation, with elevated serum levels being a strong independent predictor of cardiovascular disease in asymptomatic individuals." (PMID 29706967, 2018). "CRP is used for standard clinical practice and is one of the most well-known biomarkers in cardiovascular diseases." (PMID 29597295, 2018). "IL-1β, TNF-α, and IL-6 stimulated the liver to produce high-sensitivity CRP (hs-CRP), which had a strong relationship with the recurrent events of cardiovascular diseases as shown in several randomized clinical trials." (PMID 29403392, 2018). "A recent longitudinal study confirmed that high-sensitivity C-reactive protein increased with short-term exposure to CO among 61 patients with cardiovascular disease." (PMID 30477579, 2018). "This review is focused on discussing the role of CRP in cardiovascular disease, including recent advances on the implication of CRP and its forms specifically on the pathogenesis of atherothrombosis and angiogenesis." (PMID 29552019, 2018). "Markers of inflammation, including plasma C-reactive protein (CRP), are associated with an increased risk of cardiovascular disease, and it has been suggested that this association is causal." (PMID 29146277, 2018). "C-reactive protein (CRP) has been widely studied to reveal the relevance of inflammation and cardiovascular diseases." (PMID 30223597, 2018). "C-reactive protein (CRP) is another marker that has recently been studied as a potential identifier of cardiovascular disease, using an AuNP-based SERS bioassay for detection." (PMID 29751641, 2018). "Overall, CRP contributes to cardiovascular disease by several mechanisms that deserve an in-depth analysis." (PMID 29552019, 2018). "BMI was also associated with elevated concentrations of CRP and AGP, which are markers of systemic inflammation used to indicate risk of cardiovascular disease in high‐income countries." (PMID 30047256, 2018). "The frequency of intermediate monocytes positively correlated with levels of the inflammation marker IL-6, the monocyte activation marker soluble CD14 (sCD14) and the cardiovascular disease marker high-sensitivity C-reactive protein (hs-CRP)." (PMID 29415518, 2018). "In hepatocytes, in the presence of IL-6 (produced downstream of IRAK1 in the IL-1β pathway) activated STAT3 in turn activates C-reactive protein (CRP), a widely used biomarker for cardiovascular disease risk." (PMID 30279971, 2018). "Low 25-hydroxyvitamin D (25(OH)D) and elevated C-reactive protein (CRP) concentrations are independently associated with adverse health outcomes, including cardiovascular disease (CVD)." (PMID 29320465, 2018).
cardiovascular disease (continued). "Many of them have shown a strong and consistent relationship between cardiovascular diseases and inflammation markers, such as, C-reactive protein (CRP)." (PMID 28646855, 2017). "Constant remaining in locations situated near high-traffic roads is also connected with the risk of increased CRP (C-reactive protein) concentration in peripheral blood, which is an important risk factor of CVD (cardiovascular diseases)." (PMID 28012083, 2017). "Especially, high-sensitivity C-reactive protein (hs-CRP), much higher sensitivity than CRP, has been regarded as an independent biomarker for cardiovascular disease (CVD) in clinic." (PMID 28464873, 2017). "The role of inflammatory markers in cardiovascular diseases has been studied extensively and a consistent relationship between C reactive protein and cardiovascular diseases has been established in the past." (PMID 28316378, 2017). "Lower CRP is believed to be part of the mechanism for the protective effects of physical activity against cardiovascular diseases through reduced coagulation." (PMID 29059178, 2017). "The potential clinical benefits of measuring CRP in the normal range using hs-CRP methods have been evaluated broadly in cardiovascular disease, whereas the role of hs-CRP in rheumatoid diseases has been investigated to much lesser extent." (PMID 28072726, 2017). "A previous study reported that serum sICAM-1 and CRP levels were correlated in cardiovascular disease because both of them reflected chronic inflammation." (PMID 28201944, 2017). "Obese subjects frequently exhibit metabolic disorders together with elevated inflammatory markers, such as the C-reactive protein (CRP) and alanine transferase (ALT), markers associated with an increased risk of cardiovascular disease and liver damage." (PMID 28751933, 2017). "CRP and WBC are inflammation markers which have been shown in multiple prospective epidemiological studies to predict the risk of cardiovascular disease and MetS." (PMID 28191276, 2017). "Participants using diabetic medication in this study were more likely to be overweight, to have cardiovascular diseases and higher C-reactive protein levels compared to the other participants." (PMID 29194408, 2017). "Elevated CRP is also widely used as a predictor of cardiovascular disease with a threshold of 3mg/L used to define individuals at high risk." (PMID 27386859, 2016). "While CRP is a commonly used biomarker for cardiovascular disease, its mechanistic link to the control of stability or lability in atherosclerotic plaques is not well defined." (PMID 27621811, 2016). "Increased levels of both circulating PMAs and plasma CRP have been tied to cardiovascular disease in humans." (PMID 27270163, 2016). "The study utilized the cut-off point of 3 mg/L for serum CRP levels (considered as high-risk for cardiovascular disease according to AHA/CDC guidelines) and statistical equation to compute an estimation cut-off point for salivary CRP = 1629.39 pg/mL." (PMID 27022211, 2016). "CRP promotes a secretion of triglyceride and it highly came out from patients of cardiovascular disease." (PMID 26961224, 2016). "Therefore, any woman with high baseline levels of inflammatory markers who are at risk of dying from BCa was more likely to die first from cardiovascular disease before experiencing fatal BCa, and this may explain the weaker effects of serum CRP and G/L ratio on cumulative mortality from BCa." (PMID 27294662, 2016). "In patients with T2DM and established cardiovascular disease, canakinumab reduced markers of inflammation (hs-CRP and IL-6) compared with placebo." (PMID 27737744, 2016). "Other reports about the effects of CRP on fibrosis, inflammation, atherogenesis, cardiovascular disease, and monocyte/macrophage responses are conflicting (possible reasons for which are reviewed in Scirica and Morrow 47)." (PMID 27621811, 2016).
cardiovascular disease (continued). "Increasing levels of ALP suggest a correlation between liver damage and cardiovascular disease, which has already been shown by others regarding liver enzymes and C-reactive protein levels." (PMID 26635912, 2016). "The increased cardiovascular disease in RA has been associated with more multisystem involvement and higher inflammation as measured by ESR and CRP." (PMID 26180748, 2015). "C-reactive protein (CRP) is a circulating biomarker of inflammation, and its level is a consistent risk factor for MI and cardiovascular disease." (PMID 26658659, 2015). "In this study, we chose CRP as the marker of systemic inflammation because its relation with cardiovascular disease in dialysis patient is well reported." (PMID 26010741, 2015). "The HR for cardiovascular disease of albumin, CRP, and previous history of vascular disease was 2.040, 1.893, and 6.41 respectively." (PMID 26194096, 2015). "In a recent paper, HD patients receiving a daily dose of ALA (600 mg) for 8 weeks reported only a reduction in C-reactive protein (CRP) level, which is a risk factor for cardiovascular disease in this patients’ population." (PMID 26612997, 2015). "Literature data show a strong link between LEP and increased CRP independently of body weight and the occurrence of cardiovascular disease." (PMID 26389928, 2015). "In the case of cardiovascular diseases, markers in the blood, such as myoglobin, C-reactive protein, l-homocysteine and thrombin have been used to select DNA aptamer for the diagnosis of related diseases." (PMID 26610462, 2015). "An association between CRP and ESR levels as well as neopterin concentrations has been shown already earlier in patients with other diseases such as cardiovascular disease and malignancies as well as in patients with RA." (PMID 26576067, 2015). "Studies have demonstrated an inverse correlation between CRP concentration and cardiovascular disease in both type 1 and type 2 diabetes." (PMID 27429271, 2014). "The only smaller animal model that seems to be useful for studying CRP biology and its role in cardiovascular disease is the rabbit model." (PMID 24799767, 2014). "Apart from diabetic disorders, single nucleotide polymorphisms (SNPs) in the HNF1a have also been linked to changes in plasma concentrations of the C-reactive protein (CRP), arguably a powerful risk marker for cardiovascular disease." (PMID 25057215, 2014). "A slightly increased CRP level, also known as low-grade inflammation (LGI), is associated with increased risk of several diseases, especially cardiovascular disease." (PMID 24516611, 2014). "C-reactive protein (CRP) performs two recognition functions that are relevant to cardiovascular disease." (PMID 24948846, 2014). "The relationship of CRP to the inflammatory aspects of cardiovascular disease (CVD) has been an area of keen interest." (PMID 24803739, 2014). "C-reactive protein (CRP) was included because it is associated with inflammation and cardiovascular disease." (PMID 24915044, 2014). "More recently, inflammation has been associated with an increased risk of cardiovascular events and the level of C-reactive protein (CRP), a marker of inflammation, predicts outcome in patients with cardiovascular disease." (PMID 24571954, 2014). "Higher levels of CRP predict cardiovascular events indicating a possible role for inflammation in the etiology of cardiovascular disease." (PMID 24563867, 2014). "Second, increased serum CRP concentration at baseline is an important predictor of subsequent death due to cardiovascular disease in patients with new-onset inflammatory polyarthritis, and it is independent of other indicators of disease severity." (PMID 25359432, 2014). "Studies have shown a link between CRP and various cardiovascular diseases such as atherosclerosis, hypertension, and chronic HF." (PMID 24885051, 2014).